ALK (ALK receptor tyrosine kinase)
Diseases named in the same sentence as ALK in open-access papers (continued):
Sharing a sentence is not in itself a finding about the gene and the disease.
cancer (continued). "At the very least, this unbiased analysis supports the hypothesis that the ALK pathway may be a valid target for therapeutic interventions in cancers of different subtypes and organs including the nervous system, breast, lung, colon, ovary, prostate, and in melanoma." (PMID 23267434, 2012). "In addition, various mutant forms of ALK have been reported in cancer." (PMID 22347506, 2012). "Activation of Anaplastic lymphoma kinase (ALK) and leukocyte tyrosine kinase (LTK) by their cognate cytokines ALKAL2 and ALKAL1 plays important roles in development, metabolism, and cancer." (PMID 40208865, 2025). "Membrane receptors, such as integrins, PTPζ, ALK, and Notch2 receptor, are reported to serve as MDK receptors in cancer cells." (PMID 40429950, 2025). "Based on a meta-analysis of published cohorts, the overall incidences of VTE with ALK, ROS1, EGFR, and wildtype cancers are 41%, 30%, 12%, and 14%, respectively." (PMID 39858040, 2025). "Gene fusions such as TPM3—NTRK1, TPM3—ALK, and TPM3—ROS1 have been identified as oncogenic drivers in various cancers." (PMID 41275415, 2025). "Contrary to the immune contexture of EGFR and ALK altered tumors, the KRAS driven NSCLC displays predominantly IE and inflamed TME types, which suggests a different route to cancer immune evasion." (PMID 40809430, 2025). "This broad distribution pattern underscores the necessity of screening for NTRK, ALK, and ROS1 fusions in cross‐cancer clinical practice, particularly for rare or refractory malignancies with limited standard treatment options." (PMID 41275415, 2025). "Here, we wanted to determine the anti-cancer efficacy of ESK440 in NB models and provide a preclinical rationale for testing ESK440 in NB patients with ALK genomic aberrations." (PMID 39900433, 2025). "Overall, compared to those of LSEC and LSCC, DR‐LSCC showed upregulated expression of microtubule stabilization genes like ALK gene, metabolic gene GSK3B, and a slight increase of hypoxia gene HIF1A in the KEGG hsa05200 cancer pathway." (PMID 40385549, 2025). "Costs of oral drugs including anti-cancer drugs such as ALK- and EGFR-targeted drugs and oral CT drugs, immunosuppressants, and non-cancer-related drugs were calculated using the prescription data." (PMID 41139898, 2025). "Background/Objective: Oncogenic tyrosine kinases (TKs) such as ALK and SRC promote cancer progression, but their effects on metabolic enzymes are still not well understood." (PMID 41154443, 2025). "According to COSMIC, 25% of recurring fusions are RTK oncofusions such as EML4::ALK and CCDC6::RET which have been extensively studied as drivers of many different cancer types." (PMID 38833619, 2025). "Intracellular signaling pathways such as ALK, BRAF/MEK, and PI3K/AKT/mTOR are essential for the growth and survival of cancer cells." (PMID 40872476, 2025). "Patients with stage IV NSQ cancer had the worst survival outcomes compared with other stages across EGFR-positive, ALK-positive, and WT subgroups (P < .001)." (PMID 38334998, 2024). "Remaining drug-tolerant persistent (DTP) cancer cells limit the efficacy of targeted therapy in EGFR, ALK and KRAS mutant non-small cell lung cancer (NSCLC)." (PMID 38702301, 2024). "We compared the effect of (S)-CRZ and (R)-CRZ on ferroptosis in several ALK+ (Karpas-299, SU-DHL-1 and H2228) or ALK− (HT-1080 and 786-O) cancer cell lines." (PMID 39134539, 2024). "We analyzed 8,805 3’ kinase gene fusions curated from the COSMIC, focusing on the seven most common kinase fusions involving ALK, RET, ROS1, NTRK1, NTRK3, ABL1, and BRAF genes found in various types of cancers." (PMID 38877018, 2024). "In cellular assays, crizotinib exhibited potent inhibitory activity against MET, ALK, and ROS1 kinases with IC50 values in the nanomolar range across various cancer cell lines." (PMID 39335535, 2024).
cancer (continued). "This case report marks the first instance of a patient diagnosed with RET aberrant cancer exhibiting both NTRK and ALK fusions, who underwent treatment with an NTRK inhibitor and subsequently with an NTRK/ALK inhibitor." (PMID 38438731, 2024). "The same study also reported that there were two instances of ALK fusions within SDC, whereby numerous ALK gene fusion partners had been previously observed in diverse cancer types." (PMID 38966479, 2024). "We have outlined a potential treatment pathway involving sequential ALK-TKI targeted therapies and successive local interventions to control the cancer." (PMID 39931211, 2024). "Tumorigenic functions of multiple kinase fusion genes, including ABL, ALK, ROS1, RET and NTRK, are extensively targeted for cancer therapeutics." (PMID 39090739, 2024). "At this point, MYCN, ALK, RET and Phox2B built a complex network involved in different types of cancer, mostly involving the nervous system, also in regard to NF-κB (RelA/p65)." (PMID 38666930, 2024). "By cross-referencing these sources, we identified five top oncogenes—ALK, EGFR, GNAS, KRAS, and PIK3CA —due to their frequent occurrence and their critical roles in multiple cancers." (PMID 39684787, 2024). "Anaplastic lymphoma kinase (ALK) is a significant molecular target in the receptor tyrosine kinase family, holding vast relevance in drug discovery, particularly for cancer treatments." (PMID 39273340, 2024). "Here, we investigate the kinase responses in EML4-ALK V1 and V3-harbouring NSCLC cancer cells after acute inhibition with ALK TKI, lorlatinib (LOR)." (PMID 39695132, 2024). "Specifically, patients who received two or more ALK TKIs had significantly longer mOS compared to those who received only one ALK TKI and other cancer regimens." (PMID 39851929, 2024). "The findings revealed that cells expressing these variants resisted individual treatments but responded positively to a combination of ALK and EGFR inhibitors, showing elevated effectiveness in killing cancer cells." (PMID 38397899, 2024). "The median OS for stage IV NSQ cancer was 34.6 months (95% CI, 32.2-36.1 months), 56.4 months (95% CI, not reached), and 12.0 months (95% CI, 11.4-12.8 months), for EGFR-positive, ALK-positive, and WT subgroups, respectively (eTable 3 in Supplement 1)." (PMID 38334998, 2024). "Among patients with NSQ cancer and known EGFR and ALK status, 5304 individuals (40.5%) were WT, 6866 individuals (52.5%) were EGFR-positive, and 914 individuals (7.0%) were ALK-positive." (PMID 38334998, 2024). "Primary resistance, defined as the lack of initial responses to TKIs, has been observed in 20−30% of advanced EGFR‐mutant NSCLC patients, 20−40% advanced ALK‐positive NSCLC patients, 10% GIST patients, and other cancer patients." (PMID 39184861, 2024). "Clinical trials have shown remarkable effectiveness in several cancers, particularly in NSCLC and other tumors carrying fusion ALK genes or amplified c-MET genes." (PMID 38397899, 2024). "The significance of solo-LTR-derived mRNAs has been established in various cancers, such as interferon regulatory factor-5 (IRF5) and anaplastic lymphoma kinase (ALK) isoform ALKATI." (PMID 38606358, 2024). "Targeted therapy is a specialized cancer treatment that uses drugs to target specific mutant proteins, such as EGFR, ALK, and ROS1, which drive the growth of cancer cells." (PMID 38254898, 2024). "Differentiating between ALK- ALCL and carcinomas can be challenging due to potential morphological overlap, particularly in poorly differentiated cases." (PMID 39610919, 2024). "A variety of effective and well-tolerated TKIs targets, including EGFR, ALK, ROSI, HER2, etc., have emerged continuously, and promoted significant progress in cancer treatment." (PMID 36798829, 2023). "A phase I/II children’s oncology group study of 26 ALK-altered ALCL and 14 IMT pediatric patients showed promising activity of crizotinib in these cancers." (PMID 37773318, 2023).
cancer (continued). "Several oncogenic driver mutations, e.g., epidermal growth factor receptor (EGFR; 15–20% of NSCLCs) and anaplastic lymphoma kinase (ALK; 5% of NSCLCs), have been shown to promote cell transformation and cancer growth and progression." (PMID 37543587, 2023). "How ALK activity impacts on EML4-ALK variant protein levels is unclear, although interactions with proteins such as the HSP90 chaperone that is critical for protecting proteins from degradation as well as maintaining the activity and stability of oncoproteins in cancers may be of importance." (PMID 38264745, 2023). "The aim of this review is to summarize generations of ALK tyrosine kinase inhibitors (TKI), present their efficacy and anti-cancer properties, and to discuss various mechanisms of resistance." (PMID 37954850, 2023). "We screened an anti-cancer compound library and identified fibroblast growth factor receptor 1 (FGFR1) promoting alectinib-induced anaplastic lymphoma kinase (ALK) fusion-positive DTP cell’s survival." (PMID 37880373, 2023). "Socioeconomic level, QoL, GTV, and TNM were present in all the models, while ALK expression, CTV, primary symptom, and family cancer history were present in 4 out of 6 models." (PMID 37251617, 2023). "In comparison with ALK‐TKIs monotherapy, the combined treatment with afatinib, a pan‐HER inhibitor, and ALK‐TKI has the potential to suppress cancer development and eradicate DTCs." (PMID 37638338, 2023). "A group of isolated cancer patients with neuropathic pain showed a significant response to EGFR inhibitors, while a meta-analysis of ALK inhibitors intended to treat NSCLC revealed that a subgroup of patients experienced reduced musculoskeletal pain." (PMID 37892172, 2023). "Targeting ALK and EGFR can effectively improve the quality of life and survival time of cancer patients." (PMID 36903251, 2023). "HER3 expression data were only available for five cases of ALK-translocated NSCLC, and these were compared with NSCLC cancers with adenocarcinoma histology." (PMID 37722715, 2023). "Customized probes were designed to capture exonic regions of 141 genes selected for the panel, which was aimed for the detection of clinically actionable genetic variations in cancer, including KRAS, NRAS, BRAF, ALK, ROS1, KIT and EGFR." (PMID 35446881, 2022). "In this study, we used an AI-based solution to detect ALK and ROS1 fusions in NSCLC cancer patients." (PMID 36057739, 2022). "Stemming from these observations, we propose a model in which an autocrine loop of ALKAL2-mediated ALK activation, by signaling through the AKT downstream cascade, is responsible for the CMS1 cancer progression." (PMID 35351152, 2022). "Fusions have proven to be attractive drug targets in the case of ALK, NTRK, and FGFR fusions, leading to the development and approval of efficacious novel drugs for other cancers." (PMID 35326655, 2022). "Since then, more than 20 different ALK fusion proteins have been found in different cancers, for example, EML4‐ALK in NSCLC." (PMID 34845836, 2022). "We selected 17 human cancer cell lines with known mutant genes, such as EGFR, VEGF, BRAF, ALK, and HER2." (PMID 36313330, 2022). "Thus, ALK-altered cancer cells may potentially trigger antibody responses in patients." (PMID 35958559, 2022). "EGFR, HER2, ALK, AXL, FLT3, PDGFR and other receptors and signal transducers (e.g., Raf) are involved in the metastasis of various cancers." (PMID 35477123, 2022). "Of these DEGs, 6 (EGFR, GATA3, DIABLO, CFLAR, RIPK3, and MAPK8) were repressed, while (ZBP1, PLK1, SPATA2, BCL2, ALK, FASLG, TNFRSF21, and LEF1) were upregulated in cancer cases." (PMID 35610275, 2022).
cancer (continued). "Many studies have shown that ALK is a specific target for cancer therapy, and ALK inhibitors have been approved for use in the treatment of patients with advanced NSCLC who are confirmed to have ALK arrangements." (PMID 36167821, 2022). "Mutations in multiple genes, including epidermal growth factor receptor (EGFR), anaplastic lymphoma kinase (ALK), ROS1, and KRAS, can promote the progression of this cancer." (PMID 36467503, 2022). "We investigated clinically relevant RTK fusion genes, namely ABL1, ALK, ERBB2, FGFR1-4, NTRK1-3, RET, and ROS1, because they are among the most frequent druggable cancer molecular biomarkers." (PMID 36009413, 2022). "We carried out a retrospective analysis of prospectively collected data of patients with ALK-rearranged NSCLC and Eastern Cooperative Oncology Group (ECOG) PS of 2–4 treated at a single academic cancer centre from January 2013 to November 2018." (PMID 36072236, 2022). "However, to our best knowledge, there is no report of an ALK-HLA-DRB1 fusion variant in any cancer." (PMID 35280798, 2022). "Compared with other molecules directly downstream of ALK, such as Smad4, STAT3, PI3K and PLC-γ, TOPK is a better target for cancer therapy." (PMID 36167821, 2022). "PIM1 is an established oncogenic driver, and its inhibition was shown to re-sensitize cancer cells to radiotherapy as well as c-MET and ALK inhibition in NSCLC tumors." (PMID 35360705, 2022). "These obtained opto-PROTACs were able to degrade IKZF1/3, BRDs or ALK fusion protein (using corresponding POI ligands) upon 365 nm UV irradiation, inhibiting cancer cell proliferation in an optical-controlled manner." (PMID 35410300, 2022). "Moreover, a down-regulation of feature “variance” was observed in ALK-translocated (n = 2) vs wild-type (n = 109) cancers (4.60 vs 8.64; p = 0.0282), but there was no differentially expressed features regarding KRAS-mutated (n = 27) vs wild-type (n = 88) cancers." (PMID 35482262, 2022). "We used two cancer cell lines that express oncogenic KRas, and two cell lines that have EML4/ALK as the oncogenic driver." (PMID 36686777, 2022). "The novel and unique patient’s cancer cell line JVE404 showed response, in terms of viability and reduction in cell signaling effectors, to ALK inhibitors in vitro." (PMID 33878728, 2021). "The activated ALK fusion protein leads to abnormal ALK signaling through several molecular signaling pathways, including PI3K/AKT/mTOR, JAK/STAT, and RAS/MEK/ERK, and finally leads to cancer." (PMID 34150615, 2021). "The specific SHP2 inhibitor, SHP099, effectively suppressed the growth of receptor–tyrosine–kinase‐driven cancers in mouse xenograft models and prevented cancer resistance to inhibitors of MEK and anaplastic lymphoma kinase (ALK)." (PMID 34102002, 2021). "Among the 343 ALK fusion cases, complex ALK rearrangements in 14 cases were identified using targeted DNA-based NGS across 86 cancer-related genes panel with multiple probes tilling selected intronic regions of fusion partner genes." (PMID 34271921, 2021). "Brigatinib is a dual kinase inhibitor that targets mutant epidermal growth factor receptor (EGFR) and anaplastic lymphoma kinase (ALK) and is an approved drug for cancer therapy." (PMID 34642691, 2021). "Most pediatric ALCL cases carry ALK gene fusions (ALK-positive ALCL) that constitutively activate RAS-ERK, JAK3-STAT3 and PI3K–Akt oncogenic signaling pathways, thus promoting cancer cell proliferation, differentiation, and survival." (PMID 34113568, 2021). "Such insights will enable translational research toward interventions that successfully target the cellular function of ALK and LTK in human cancers." (PMID 33196781, 2021). "Similar to ALK, another oncogenic RTK, RET, also undergoes multiple distinct and recurrent gene rearrangements in human cancer, leading to the elimination of the extracellular and transmembrane domains from the various fusion oncoproteins." (PMID 33848463, 2021).
cancer (continued). "While ALK TKIs have significantly improved the prognosis of patients with advanced ALK-rearranged NSCLC, these cancers remain incurable." (PMID 33806977, 2021). "To study the adaptive changes during targeted inhibition of oncogenic signaling we exposed cancer cells (n = 9) driven by diverse activated kinases (EGFR, MET, BRAF, HER2, ALK) to targeted drugs and performed transcriptional profiling using RNA-seq." (PMID 34535668, 2021). "Rare cases of ALK- ALCL can be focally positive for cytokeratins and misdiagnosed as a poorly differentiated carcinoma, particularly if EMA is also positive (inset)." (PMID 34572893, 2021). "In some cancers, mutant forms of NPM1 including the one fused to ALK, anaplastic lymphoma receptor tyrosine kinase, and NPM1c+ (NPM1 cytoplasmic positive) are known." (PMID 33050036, 2020). "ROS1-positive cancers show overlapping clinical features with ALK-rearranged NSCLC, although genetic rearrangements in ROS1, EGFR and ALK tend to be mutually exclusive." (PMID 33172113, 2020). "Remarkable success has been achieved by targeting oncogenic gene fusions including diverse tyrosine kinase inhibitors against fusions involving ALK, ROS1, RET, FGFR1/2/3, and NTRK1/2/3 in non-small-cell lung cancer and across a wide spectrum of cancer types." (PMID 32411236, 2020). "Given the importance of activated ALK signalling and since ALK fusion genes also achieve enhanced signalling in ALCL and NSCLC, we investigated ALK-induced ETV5 expression in these cancer entities." (PMID 31937834, 2020). "Anaplastic lymphoma kinase (ALK), a receptor-type tyrosine kinase, is involved in the pathogenesis of several cancers." (PMID 32344689, 2020). "In a cancer context, MDK has been proposed to promote resistance to anticancer treatments via ALK stimulation." (PMID 32308772, 2020). "There are developed targeted therapy by targeting cancer driver genes such as epidermal growth factor receptor (EGFR) and anaplastic lymphoma kinase (ALK)." (PMID 33238593, 2020). "We found that across all three groups 81% of patients with a known molecular target (EGFR, ALK, ROS or BRAF) received a TKI, 91% if considering only those patients who received any cancer specific treatment." (PMID 32470017, 2020). "Among these cancers, ALK gene fusions were identified to be most common in ALCL (60% cases, mainly NPM-ALK fusion), followed by IMT (~50% cases, mainly TPM3/4-ALK fusion), NSCLC (~5–7% cases, mainly EML4-ALK fusion), and other cancers." (PMID 32059449, 2020). "Different kinases, such as anaplastic lymphoma kinase (ALK), Aurora kinase, RET receptor tyrosine kinase, are potential therapeutic targets in various cancers, including NB." (PMID 32336043, 2020). "Given their robust oncogenic drive and pharmacologic targetability, kinase fusions have garnered substantial attention as therapeutic targets in cancer, including the noteworthy first fusion to be targeted, BCR-ABL, followed by ALK, ROS1, and NTRK fusions." (PMID 33328556, 2020). "Crizotinib is an ATP-competitive inhibitor targeting ALK/ROS1/c-MET kinases that has been approved by the FDA as a first-line chemical for the treatment of NSCLC and other cancers with ALK rearrangement, ROS1 rearrangement, or aberrant activation of c-MET2-5." (PMID 32792859, 2020). "A multi-kinase inhibitor CT-707 that predominantly inhibits FAK, anaplastic lymphoma kinase (ALK) and PYK2 is able to render cancer cells vulnerable to hypoxia through YAP inhibition." (PMID 32206112, 2020). "This provides the rationale for a sequential TRK inhibitor treatment approach in patients with TRK fusion cancer, similar to current practice in oncogene-addicted (e.g. EGFR, ALK) NSCLC." (PMID 32891793, 2020). "In fact, these findings are consistent with the notably low immune infiltrating levels in ALK-rearranged NSCLC tumors, supportive of the notion that ALK-altered cancers can be immunosuppressive in their microenvironments." (PMID 32059449, 2020).